RNU6-1089P (RNA, U6 small nuclear 1089, pseudogene)
Gene: Small nuclear RNA gene on chromosome 1 (245,023,015 to 245,023,118, forward strand). Ensembl gene ENSG00000252282.
Homologues: Orthologues: chimpanzee U6 (99% identical), macaque U6 (95% identical), dog U6 (88% identical), rabbit U6 (88% identical), zebrafish U6 (76% identical). Paralogues in human: RNU6-1145P (91% identical), RNU6-11P (91% identical), RNU6-16P (91% identical), RNU6-37P (91% identical), RNU6-812P (91% identical), RNU6-20P (90% identical), RNU6-25P (90% identical), RNU6-29P (90% identical), RNU6-38P (90% identical), RNU6-393P (90% identical), RNU6-41P (90% identical), RNU6-940P (90% identical), and 1286 more.